SPP1 (secreted phosphoprotein 1)
Diseases named in the same sentence as SPP1 in open-access papers (continued):
Sharing a sentence is not in itself a finding about the gene and the disease.
infection (continued). "(I) Differential interaction strengths of a cellular interactome for TNF, SPP1, and CXCL signaling pathways between all cell types in infection." (PMID 38767331, 2024). "In contrast, the life-span of the mutants that are defective in age-1 (hx546), spp-1 (ok2703), or dbl-1 (nk3) were more resistant to DT104 infection with an increased life-span compare with the WT nematode." (PMID 33763087, 2021). "The systems biology analysis identified multiple immune system and inflammation molecules (e.g., STAT3, STAT1, CEBPB, JUN, IGF1, SPP1, NFKB2, IL-1β, and CSF1) as master regulators that are activated upon infection." (PMID 26865111, 2016). "Using larvae from the spp1 knockout, we found no increase in mycobacterial burden during the initial stages of infection." (PMID 40772762, 2025). "Pseudotime analysis indicated that classical and non-classical monocytes move toward the Spp1+ lineage after infection, and Spp1 expression is highest at the termination of lineage three." (PMID 40704794, 2025). "In our data, the SPP1 signal was predominantly emitted by renal tubular cells and received by T cells, indicating an immunomodulatory role of renal tubular cells on T cells post-IBV infection." (PMID 38743760, 2024). "The finding that SPP1 infectious particles are assembled in vitro in absence of gp16.1 prompted us to investigate their formation during infection with the SPP1gp16.1− conditional lethal mutant." (PMID 38755280, 2024). "Phage particles produced in non-permissive and in permissive infections with SPP1gp16.1− have amounts of gp19.1 and gp17 similar to SPP1 wild type particles, confirming correct tail assembly." (PMID 38755280, 2024). "Tails assembled in absence of gp17, of gp16.1, of both proteins, and of SPP1 capsids purified from infection with appropriate sus mutants (this work) were used as controls." (PMID 38755280, 2024). "Despite these matrix-dependent effects, the mRNA levels of Opg, Bmp2, and Spp1 did not change significantly during the infection, consistent with the reported antiosteogenic effects of inflammation and infection." (PMID 34357987, 2021). "In contrast to these observations, the mutant defective in spp-1 became more susceptible to DT104 infection after LB1 pretreatment, which was more resistant to the infection without LB1 pretreatment." (PMID 33763087, 2021). "We found that SPP1 was upregulated in non-infected cells, suggesting that the presence of SPP1 induces distant antiviral responses that protect cells from further infection." (PMID 33504604, 2021). "Toxin ζ induces an active slow-growth state that halts SPP1 amplification, but it re-starts after antitoxin expression rather than promoting abortive infection." (PMID 33333975, 2020). "The study of SPP1 in cells where toxin ζ is expressed reveals that ζ induces an active slow-growth rather than a growth-arrested condition and abortive infection." (PMID 33333975, 2020). "Although trends toward decreased Spp1 expression were observed following AdV-Sox9 infection, significant changes were not achieved." (PMID 22046352, 2011). "The expression of abf-2 and spp-1 was induced following infection by the Gram-negative bacterium Salmonella typhimurium, and both genes were required to protect against S. typhimurium infection." (PMID 18927620, 2008). "In SPP1 infection, there is no membrane nor proteinaceous shell surrounding these compartments." (PMID 41922332, 2026). "Given our observation that infection-specific keratinocyte populations were involved in ECM remodeling and immune response, we hypothesized that these cells might participate in the SPP1 signaling pathway." (PMID 38767331, 2024). "However, like thn-2, spp-1, and lys-7, knockdown of skn-1 expression by RNAi does not abolish the downregulation of gst-4 following PA14 infection, despite causing a reduction in the basal level of gst-4 expression." (PMID 18927620, 2008).
infection (continued). "Moreover, knockdown of elt-2 by RNAi reduces the expression of lys-7 and spp-1 under uninfected conditions (data not shown) and enhances the relative downregulation of thn-2 during PA14 infection." (PMID 18927620, 2008).
cardiovascular diseases (50 papers, 2010 to 2025). "It is thought that the acute increase in SPP1 has a protective role in cardiovascular disease in adults, whereas a more chronic increase predicts poor prognosis." (PMID 36139018, 2022). "In summary, SPP1 coordinates immune cell interactions, drives cell phenotypic transformation, and promotes pathological tissue remodeling, thereby affecting ECM dynamics and becoming a common pathogenic factor in the progression of multiple cardiovascular diseases." (PMID 41293726, 2025). "SPP1 is known to impact not only AKI and CKD but also several cardiovascular diseases." (PMID 38768139, 2024).
neurodegenerative disease (41 papers, 2010 to 2026). A disorder of the central nervous system characterized by gradual and progressive loss of neural tissue and neurologic function. "24.2% of microglia differentially expressed genes such as Gpnmb, Spp1, and Fabp5, which are associated with neurodegenerative diseases, thus we called this population Disease-Associated35,36." (PMID 40501958, 2025). "Secreted phosphoprotein-1 (SPP1/OPN), by virtue of its modular domain structure, is a multifunctional phosphoprotein implicated in several neurodegenerative diseases." (PMID 38646526, 2024). "Spp1 has been shown to be implicated in inflammatory and degenerative diseases of the nervous system." (PMID 33167585, 2020). "Interestingly, we also detected reductions in disease-associated microglia (DAM)/microglial neurodegenerative disease (MGnD) genes such as Cst7, Clec7a, and Spp1, suggesting that microglia adopted a dampened DAM/MGnD state despite no changes in IBA1+ microglia staining." (PMID 36922879, 2023). "Elevations in SPP1 have been identified in numerous neurodegenerative disease contexts in acute and chronic neuroinflammation, as a marker of CNS injury." (PMID 41256000, 2025). "The increase in secreted protein levels like chitinase 3 like 1 (CHI3L1) and osteopontin (SPP1) was observed in patients with pathology of AD and neurodegenerative disease." (PMID 36793451, 2023). "Another group-enriched protein connected with neurodegenerative diseases and observed with high abundance is a glycosylated phosphoprotein SPP1." (PMID 27186164, 2016). "Supporting our observation, studies have indicated that in the context of aging and neurodegenerative diseases, OXPHOS dysfunction is a primary cause of energy insufficiency in MG, suggesting that Spp1 plays an essential role in maintaining OXPHOS‐mediated energy metabolism in MG." (PMID 41549460, 2026). "Beyond musculoskeletal systems, SPP1+ macrophages also influence neurodegenerative diseases." (PMID 40047497, 2025). "Similarly, Spp1 is a proinflammatory cytokine that is involved in various neurodegenerative diseases including AD." (PMID 36271414, 2022). "This suggests that Spp1 is markedly increased in the common neurodegenerative disease; AD." (PMID 33167585, 2020).
kidney disease (40 papers, 2004 to 2025). "In the past several specific SPP1 gene variants have been associated with the pathogenesis and progression of different kidney diseases." (PMID 35385482, 2022). "The role of SPP1 variants in kidney diseases needs to be better explored as a diagnostic target to monitor these conditions." (PMID 31159229, 2019). "Other case-control studies reported on specific variants in the SPP1 gene being associated with different kidney disease patients in comparison to a (healthy) control group: For example, rs1126616 was repeatedly reported as a marker for lupus nephritis and immunoglobulin A nephropathy." (PMID 35385482, 2022). "SPP1, as a damage-associated molecule, is elevated in AKI and other renal diseases, and has also been observed in injuries to other organs." (PMID 41476974, 2025). "SPP1 has already been identified as a relevant ligand playing a significant role in kidney disease in our study." (PMID 38768139, 2024). "SPP1 mRNA as well as OPN protein expression were elevated in mostly rat models of kidney diseases and high OPN expression correlated with proteinuria, reduced kidney function, and fibrosis." (PMID 35385482, 2022). "For this review, we used the search string “((kidney[Title/Abstract]) OR (renal[Title/Abstract])) AND ((SPP1[Title/Abstract]) OR (Osteopontin[Title/Abstract]))” to retrieve studies on OPN and human kidney diseases from the PubMed database published between January 1, 2010, and June 1, 2024." (PMID 40093009, 2025). "Among the remaining proteins, S100a9 and Spp1 have clear functions in kidney disease." (PMID 39911133, 2025).
adenocarcinoma (19 papers, 2005 to 2026). A common cancer characterized by the presence of malignant glandular cells. "The univariate Cox regression analysis revealed that some factors, including male sex, smoking, a high pathological stage, the EGFR-wild-type status, and a high score for SPP1 on TAMs, were associated with a shorter CSS in adenocarcinoma." (PMID 36139536, 2022). "The glycoprotein osteopontin SPP1 was also identified as differentially expressed in both squamous and adenocarcinoma tumors." (PMID 36404344, 2022). "We observed three predominant macrophage states: an antigen-presenting C1QC+ state predominant in the normal colon, a pro-inflammatory IL1B+ state predominantly found in the normal liver, but also in normal colon and adenocarcinoma, and finally, a SPP1+ state enriched in tumors." (PMID 38036590, 2023). "Interestingly, high expression of SPP1 in TAMs was associated with worse clinical course in patients with adenocarcinoma, especially in cases without EGFR mutations." (PMID 37190178, 2023).
inflammation (15 papers, 2010 to 2025). Aberrant reaction of the microcirculation characterized by movement of fluid and leukocytes from the blood into extravascular tissues. "The results support the effects of ISOF via the cAMP/AQP4/SPP1/PIK3C3 axis on chronic airway inflammation, demonstrate its potential to reduce Th17 differentiation and thus the Th17/Treg balance, and provide potential targets for the treatment of this disease." (PMID 37817209, 2023).
bacterial infections (14 papers, 2006 to 2025). "Deficiencies in GLA and SDA result in increased susceptibility to bacterial infection, which is associated with reduced basal expression of a number of immune-specific genes—including spp-1, lys-7, and lys-2—that encode antimicrobial peptides." (PMID 19023415, 2008). "Several cells express Spp1 following viral or bacterial infection, including dendritic cells, T cells and macrophages, and it functions as a cytokine and anti-apoptotic growth factor, involved in adhesion, chemotaxis, cell differentiation and inflammation." (PMID 17183687, 2006). "Indeed, knockout SPP1-/- mice have shown significantly impaired Th1 immunity to viral and bacterial infections with diminished production of interleukin-12 (IL-12) and interferon-gamma (IFN-γ) and elevated production of interleukin-10 (IL-10)." (PMID 19765294, 2009).
neurological diseases (12 papers, 2013 to 2025). "Most studies to date have consistently demonstrated the neuroprotective effects of SPP1 on neurological disorders." (PMID 39939834, 2025). "Studies have shown that SPP1 is highly expressed in various models of neurological diseases, and it participates in different inflammatory responses by regulating immune cells." (PMID 40417312, 2025). "In the realm of aging research, SPP1 has predominantly been explored within the context of neurological disorders." (PMID 38248779, 2024). "Therefore, our study demonstrating a functionalrole for SPP1 in microglia–synapse phagocytosis will likely have broadrelevance to understanding neuroimmune mechanisms of synapse vulnerability in AD andother neurologic diseases involving synaptopathy." (PMID 36747024, 2023).
heart disease (10 papers, 2011 to 2025). "Accumulating studies have confirmed that VC is involved in the inflammatory response in heart disease, and SPP1+ macrophages play an important role in this process." (PMID 38919629, 2024).
metabolic disorders (10 papers, 2015 to 2025). "Gene annotation based on the TWAS database highlighted significant associations between several of these candidate genes (such as SPP1, FAM13A, NDRG1, and IER3) and key bovine health traits, including milk protein percentage, body depth, and ketosis (a metabolic disease of dairy cow) susceptibility." (PMID 40521032, 2025). "The correlation between AKR1B10, SPP1, B cells, DCs, and MAIT cells indicated the possible interactive network structure that may explain and control metabolic disorders and fibrotic phenotypes from NASH to HCC." (PMID 33574818, 2020).
prostate (9 papers, 2016 to 2025). "Moreover, we showed that the expression of numerous genes was increased by CSF-1 in prostate cancer cells, including the spp1 gene that encodes for osteopontin, a major actor in prostate carcinogenesis." (PMID 36555673, 2022).
bone disorder (5 papers, 2016 to 2025). "Results from our colocalization analysis using GeneAtlas are pointing towards a connection of SPP1 with bone disorders." (PMID 35385482, 2022).
respiratory diseases (5 papers, 2013 to 2025). "By exploring the diverse roles of SPP1 in these conditions, this review will highlight the potential of SPP1 as both a diagnostic and prognostic biomarker, as well as a therapeutic target in respiratory diseases, particularly for ILDs." (PMID 40559389, 2025). "Finally, PIK3C3 has also been found to be partially regulated by SPP1 in respiratory diseases after altering the inflammatory environment via AKT-MTOR." (PMID 37817209, 2023). "Therefore, elevated expression of SPP1 in the small airway epithelium of smokers may have significant long term pathological consequences and may play a key role in the process of airway remodeling characterized in smoking-induced respiratory disease such as COPD." (PMID 25248511, 2014).
intestinal diseases (3 papers, 2022 to 2025). "Up-regulated EREG, SPP1, and PTGS2 by CotG-p40 support the claim that it can protect intestinal epithelial cells from intestinal diseases." (PMID 36550414, 2022).
retinopathy (3 papers, 2016 to 2023). "In addition to Spp1 and CD11c, Macs with increased glycolytic flux are detectable in retinal neovascularization from the oxygen-induced retinopathy model and during laser-induced CNV." (PMID 36821388, 2023).
head and neck tumor (2 papers, 2019 to 2024). "IHC database showed the protein expression of TGFBI, SPP1, and LAMB3 in head and neck tumor tissues were up-regulated compared with normal tissues." (PMID 31485443, 2019).
animal disease (1 paper, 2023). "In fact, gender differences in SPP1 expression were found in both human and animal disease models, with higher expression levels in males than in females, which was consistent with our results." (PMID 37491214, 2023).
SPP1 also shares sentences with these, for which no sentence is quoted: idiopathic pulmonary fibrosis (34 papers); Crohn disease (17); Myocardial fibrosis (15); acute kidney injury (13); dementia (12); lupus nephritis (12); acute myeloid leukemia (11); alcoholic liver diseases (11); infectious disease (11); peripheral artery disease (11); acute myocardial infarction (9); bone metastasis (8); Hepatitis (8); inflammatory bowel disease (8); kidney failure (8); acute coronary syndrome (7); acute lymphoblastic leukemia (7); injury (7); kidney cancer (7); non alcoholic fatty liver disease (7); amyotrophic lateral sclerosis (6); chronic pancreatitis (6); hepatitis C (6); infarction (6); meningioma (6); Osteopenia (6); renal failure (6); respiratory failure (6); skin cancer (6); abdominal aortic aneurysm (5).
A further 414 diseases each share a sentence with SPP1 in 5 papers or fewer.